CD44 (CD44 molecule (IN blood group))
Diseases named in the same sentence as CD44 in open-access papers (continued):
Sharing a sentence is not in itself a finding about the gene and the disease.
glioma (continued). "Beside HA and CD44 upregulation, human glioma tissues display high level of hyaluronic acid synthase 3 (HAS3), which negatively correlated with the prognosis glioma patients." (PMID 38969910, 2024). "This study elucidates Shikonin's capacity to effectively induce necroptosis in glioma cells, concurrently mitigating glioma stemness, as evidenced by diminished levels of stem cell markers, namely SOX2, CD44, CHI3L1, and CD24." (PMID 39619148, 2024). "ZBTB42 is positively related to glioma stem cells marker genes such as CD44, MSI1, Fut4, and NES and the high expression group has a stronger relationship with glioma stemness." (PMID 36762114, 2023). "In glioma, EMP1 regulates the cell proliferation, migration, and stemness through PI3K-AKT signaling and CD44." (PMID 37008256, 2023). "The median stiffness depends on glioma cell types and decreases according to the following manner: IDH1 R132H mt (4.7 mN/m), CD44+/IDH1wt (3.7 mN/m), CD44-/IDH1wt (2.5 mN/m)." (PMID 36835465, 2023). "Western blotting was used to show that the expression of Wnt/β‐catenin pathway‐related proteins, including β‐catenin, c‐Myc, cyclin D1, CD44 and Met, was remarkably decreased in NSC‐CM‐treated glioma cells." (PMID 37410396, 2023). "As expected, GSCAR expression positively correlated with glioma stem cell biomarkers, including CD133, CD44, NANOG, ALDH1, Oct4, SOX2, and c-Myc." (PMID 37063420, 2023). "High CD44 expression correlates with unmethylated MGMT promoter, suggesting that CD44+ glioma cells confer TMZ resistance." (PMID 36989359, 2023). "Both LSPR and AFM have high sensitivity and specificity, and can detect and quantify raised levels of CD44 and CD133 in immunocaptured glioma-derived exosomes in the blood and CSF of animal models." (PMID 37122733, 2023). "We demonstrated that CNIH4 has a significant effect on GSC markers (CD144, CD44, and BMI1) via knocking down CNIH4 by using specific shRNAs, implying that CNIH4 as a definite therapeutic target in glioma stem cells." (PMID 37062068, 2023). "The levels of CD44 and CD133 were shown to be elevated in exosomes in anoxic environments, promoting glioma migration and lumen formation by endothelial cells." (PMID 37122733, 2023). "Finally, RUNX1/CD44 axis could promote the proliferation and migration of gliomas." (PMID 36776876, 2023). "CD44-HA mediated cell invasion can be modulated by EGFR, a well-known receptor overexpressed in gliomas." (PMID 36980765, 2023). "SPP1 was also recognized as a ligand for CD44, and SPP1-CD44 communication augmented the stemness of CD44 secretory glioma-stimulatory cells." (PMID 35419058, 2022). "It is interesting to note that, upon direct TLR2 stimulation, CD44-/- microglia were still able to increase MMP9 production, while this ability was completely abolished in the presence of glioma cells." (PMID 35992852, 2022). "Molecularly, hyaluronic acid binds to different membrane receptors including the glycoprotein receptor CD44 and the receptor for hyaluronan-mediated motility (RHAMM), which has a central role in glioma cell motility, invasion, and inflammation." (PMID 36276147, 2022). "Primary microglia isolated from WT or CD44-/- mice were seeded in the bottom compartment, while adherently growing GL261 mouse glioma cells were seeded in the top compartment and their migration was assessed after 24 hours." (PMID 35992852, 2022). "Co-culture of mast cells with glioma cells induces the expression of serglycin, CD44, ZEB1, vimentin, CXCL10, CXCL12, and TNF-α in glioma cells and IL-6 and CXCL1 in mast cells, creating an inflammatory milieu that induce glioma cell aggressiveness." (PMID 35494005, 2022). "Recently, ABCC3 has been included in gene signatures (ABCC3, CD44, TNFRSF1A, and MGMT24; ABCC3, SMC4, EMP3, WEE1, and HIST1H2BK44) that classify glioma patients in agreement with therapeutic response to chemotherapeutic agents, including TMZ." (PMID 36585418, 2022).
glioma (continued). "CD44 knock-out in myeloid cells affected their ability to upregulate TNF-α and IL-1b, and most notably, to increase MMP9 production in response to gliomas." (PMID 35992852, 2022). "HIF‐2α (Hypoxia-Inducible Factor 2α) expression is also regulated by CD44‐OPN interaction through a CBP/p300‐dependent mechanism (mediated by CD44-ICD) and it has been demonstrated to promote stem-like properties and tumoral aggressiveness in glioma cells." (PMID 35785191, 2022). "On the contrary, myeloid-specific deletion of CD44 significantly reduces invasiveness, strongly suggesting that CD44 expression in myeloid cells of the TME promotes glioma invasion." (PMID 35992852, 2022). "SPP1(osteopontin)/CD44 signaling is observed in most GBM samples, and SPP1 is a well-characterized promoter of glioma aggressiveness." (PMID 35140215, 2022). "We established a risk model (which considered the expression of CDCP1 combined with CD44 and ITGAM) and verified that it can be used to predict prognosis in glioma/GBM." (PMID 35410293, 2022). "Our results highlight a role of CD44 expressed specifically by myeloid cells from the TME, in glioma invasion." (PMID 35992852, 2022). "In an earlier study in colorectal, glioma and lung carcinoma cell lines, CD44 and PKM2 were shown to directly interact, and CD44 ablation suppressed Tyr105 phosphorylation, thereby increasing PKM2 activity." (PMID 35054968, 2022). "We also found a significant correlation between low CD44 transcription level and 1p19q codeletion status in both TCGA and CGGA glioma." (PMID 35187044, 2021). "describe a ligand-mediated mechanotransduction mechanism in gliomas that leverages the interaction between HA that is overexpressed in the ECM and CD44." (PMID 35127517, 2021). "To our surprise, we found that CD44+ T cells express both CD274 (namely PD-L1) and PDCD1 (namely PD-1) in glioma." (PMID 35187044, 2021). "Furthermore, CD44 transcription level is related to M2 macrophage infiltration at bulk-seq resolution, and this finding is verified by single-cell RNA-seq data that CD44+ TAMs are in M2-type state and by IHC that glioma with higher CD44+ cells infiltration has more infiltrating M2 macrophages." (PMID 35187044, 2021). "Our work demonstrates that CD44, a new M2 TAM biomarker, is involved in immune suppressor and promote glioma progression in glioma microenvironment." (PMID 35187044, 2021). "Whereas the LG DI tumor showed common glioma changes, such as EGFR upregulation, and ERK/MAPK and CD44/c-SRC pathway activation, the latter involved in glioma cell invasion, the HG LM component lacked these changes." (PMID 33853673, 2021). "It turns out that CD44 is significantly upregulated in GBM (WHO IV) than that in WHO grades II and III gliomas in TCGA glioma dataset." (PMID 35187044, 2021). "CD44 is positively correlated with WHO grade of malignancy and is negatively related to prognosis in glioma." (PMID 35187044, 2021). "Because CD44 was described as a marker of GBM CSCs, also known as glioma stem–progenitor cells or glioma-initiating cells, we also annotated the stem-like cells besides the six GBM tumor cellular states in malignant cells." (PMID 35187044, 2021). "HAS3 and CD44 expression were significantly decreased in glioma cells transfected with the HAS3 siRNA and CD44 siRNA, respectively, compared with control glioma cells." (PMID 33986244, 2021). "By checking expression of CD44 and CD163 in glioma samples through IF, CD44+CD163+ cells were uncovered, which confirmed that the CD44+ TAMs are in M2 phenotype." (PMID 35187044, 2021). "In glioma mouse model, CD44 was restricted to hypoxic and perivascular tumor regions, and HIF-2α, a hypoxia signature, was correlated with CD44 in human glioma." (PMID 35187044, 2021).
glioma (continued). "First, CD44 expression in both low-grade glioma (LGG) and glioblastoma (GBM) is higher than normal brain tissues, which means CD44 plays a role in glioma tumorigenesis." (PMID 35187044, 2021). "In our study, we found that anticarin β inhibits clonal spheres forming in human glioma cells and reduces the expression of stemness-related markers, such as Nanog, Oct4, Sox2, CD133, STAT3, and CD44." (PMID 34408983, 2021). "Hypoxic peri-arteriolar glioma stem cell niches exist in human glioblastoma samples, with the SDF-1α/CXCR4 signaling axis and osteopontin/CD44 interactions being involved in the homing of glioma stem cells in their niches and their maintenance." (PMID 34771577, 2021). "Therefore, we hypothesized that glioma CD44+ cells take part in tumor immunosuppression." (PMID 35187044, 2021). "We selected two commonly used and well characterised glioma stem cell markers, CD133 and CD44 in order to identify GSC subpopulations for our study." (PMID 34066147, 2021). "In glioma cells, CD44-ICD was released in a hypoxic environment and bound to hypoxia-inducible factors 2 alpha (HIF-2α) to induce stemness in glioma." (PMID 34944493, 2021). "Currently recognised specific markers for human glioma stem cells (HuGSCs) include CD133, integrin α6, CD171 (L1CAM), CD15, nestin, and CD44 1, 5-7." (PMID 32174801, 2020). "The expression of the positive MSC markers CD44, CD105 and CD29 exhibited a significant inverse correlation with the prognosis of glioma patients." (PMID 32452829, 2020). "Expression of MST1 and CD44 were negatively correlated, which demonstrated that MST1 protein levels were downregulated in mesenchymal subtype glioma tissues." (PMID 32252802, 2020). "Another recent study on high-grade glioma showed high expression of EMP3, particularly in CD44-high glioblastoma, which refuted the result of a prior study on glioma." (PMID 32857809, 2020). "To further confirm this, we investigated the correlation between the model and perinecrosis‐related genes, such as CD44, which are activated under hypoxia and interact with HIF‐2α to modulate the hypoxic phenotype of perinecrotic and perivascular glioma cells." (PMID 33009892, 2020). "Importantly, a subsequent study showed that CD44 transduces HA-based stiffness cues, temporally precedes integrin-based adhesion maturation, and facilitates invasion, demonstrating that the HA-CD44 axis is critical for cell adhesion, invasion, and mechanosensing of an HA-based matrix in glioma." (PMID 32232385, 2020). "CD44, activated under hypoxia, interacts with HIF‐2α to regulate the hypoxic phenotype of perinecrotic and perivascular glioma cells." (PMID 33009892, 2020). "ANXA2P2 was positively correlated with genes that are related to glioma proliferation, invasion and angiogenesis, such as ANXA2, CD44, IL6, MMP14, MMP9, and VEGFA." (PMID 31681595, 2019). "CD44 itself is known as a marker of GBM invasiveness and was shown to promote stem cell-like properties in glioma and to play a role in the mediation of resistance to radiation and chemotherapy with temozolomide." (PMID 31882946, 2019). "Recent studies reported that glioma cells expressing lineage markers such as A2B5, NG2, CD44, and even GFAP also meet the criteria for tumorigenic stem cells, suggesting that GIC originate from a broader spectrum of neural lineages." (PMID 31618934, 2019). "In glioma CIC, OPN-induced migration required the CD44-ICD, which enhanced CBP/p300-dependent HIF-2α activity." (PMID 30211160, 2018). "Glioma cells are now believed to originate from a neural stem cell of different commitment state, therefore “glioma stem cells” and NSCs share common phenotypic markers (CD133, CD44, CD15), as well as activated molecular pathways." (PMID 30510501, 2018).
glioma (continued). "We chose four mesenchymal transition markers (N-cadherin, ZEB1, Slug, and CD44) from the gene list identified by GSEA, which are reported to be involved in glioma mesenchymal transition, and analyzed the relationship between these markers and PBX3 expression." (PMID 30016974, 2018). "A TCGA-Glioma based co-expression study for CD133 and CD44 in glioblastomas (GBM) reported that CD133 module tumors were enriched for the Proneural GBM subtype, while CD44 module tumors were enriched in Mesenchymal subtype." (PMID 30464804, 2018). "Conversely, LGR5− glioma cells showed low expression of CD133, CD44, CD90, CD24, and EpCAM, while the expression of CD90 remained unchanged in LGR5+ and LGR5− glioma cells." (PMID 30208924, 2018). "Recent studies have described CD44 as a marker of GBM cancer stem cells, also known as glioma-initiating cells or GSCs, and CD44 expression is enriched in GSCs." (PMID 30210550, 2018). "Some intriguing aspects of the core gene set identified in this study include the well-studied glioma-related genes ANGPT2, CD44, SPP1, STAT3, PDGRFA, and TOP2A (all up-regulated), and BRSK1, DKK3, FGFR2, MAPK9, MEF2C, and PTEN (all down-regulated)." (PMID 29352201, 2018). "We found that LGR5+ glioma cells possessed considerably enhanced expression of CD133, CD44, CD90, CD24, and EpCAM." (PMID 30208924, 2018). "CD90 was recently identified as a prognostic marker for high-grade gliomas and CD44 as a marker of metastatic potential and coworkers showed that aberrant expression of the cancer stem cell markers CD90 and CD44 contributes to tumoral progression." (PMID 29774098, 2018). "The expression levels of CD133, CD44, CD24, CD90 and EpCAM were examined in LGR5+ and LGR5− U251 and 8591 glioma cells by FCM." (PMID 30208924, 2018). "Analysis of the glioma cell lines after glioma cell-mast cell (GC-MC) co-culture at different time-points indicated an increased SRGN and CD44 expression as compared when culturing glioma cells in normal cell culture media." (PMID 28445977, 2017). "In a mouse model of glioma, CD44+/+ animals developed significantly more high-grade gliomas and had shorter survival times than did CD44+/- or CD44−/− mice." (PMID 29259986, 2017). "As before we confirmed that mNS GSC have a higher expression level of the stem cell markers CXCR4, MELK, PTCH, CD44, CD133, MSl1 and CD90, while GL261 GDC expressed higher level of the differentiated glioma marker glial fibrillary acidic protein (GFAP)." (PMID 27073883, 2016). "VPA, particularly in the stem cell lines, also diminished the expression of classical stem cell markers (CD44, CD133) thus inducing a potential differentiation of glioma genotypes which is in line with a previous publication." (PMID 27556305, 2016). "After treatment with galunisertib, the expression of both ID1 and CD44 was reduced, suggesting that TGF-β signaling was inhibited in the glioma tissue." (PMID 25529192, 2015). "It has also been suggested that OPN enhances CSC-like phenotypes and promotes aggressive growth of glioma tumors through activation of HIF-2α, which occurs downstream of OPN binding to CD44." (PMID 25749383, 2015). "In glioma, OPN and CD44 share a similar perivascular expression profile, and OPN was found to promote development of glioma stem cell-like phenotypes through its action as a CD44 ligand." (PMID 25749383, 2015). "A prominent abnormality of certain malignant tumor cells, e.g., gliomas, is overexpression of the EGF receptor, and EGF induces CD44 shedding, that concomitantly enhance hyaluronan-mediated cell migration." (PMID 26347743, 2015). "In GBMs several markers have been proposed to enrich for putative glioma CSCs including CD133, CD15, CD44 and A2B5." (PMID 24154962, 2014). "To determine the expression levels of HA-receptor, CD44 and ERM protein, moesin, in NHA and glioma cell lines (U87 / U373), we carried out Western blot analysis." (PMID 23855374, 2013).
glioma (continued). "TGFβ is shown to be involved in CD44 regulation in breast CSC maintenance while interleukin 6 (IL6) can promote growth and survival of glioma stem cells." (PMID 24091605, 2013). "In the present study, the juxtaposition of CD44 and CD155 was observed on glioma cells and their interactive role in cell migration/invasion was investigated in conjunction with integrins at the cell surface." (PMID 22363471, 2012). "In accordance with previous studies, our data show that CD44 and CD155 are highly expressed in glioma cells and are closely juxtaposed on the cell membrane." (PMID 22363471, 2012). "The role of CD44 and CD155 in glioma cell invasion was investigated by two approaches: mAb-blocking and siRNA-KD." (PMID 22363471, 2012). "Another very promising therapeutic approach is the use of anti-CD44 antibodies such as IM7 which resulted in a greater than 50% decrease of HA production in glioma cells and enhanced glioma apoptosis." (PMID 21541039, 2011). "The phenotype of CTL CD8+ T cells infiltrating the brain of glioma-bearing mice treated with anti-CD25 was assessed by FACS analysis using the cell surface markers CD62L and CD44." (PMID 20339520, 2009). "Our data show that nearly all low-grade glioma cells from the analyzed cases concomitantly express multiple cell surface markers for glial progenitor cells, such as PDGFRα, A2B5, O4, and CD44." (PMID 18398462, 2008). "Six low-grade and 17 high-grade glioma specimens were flow-cytometrically analyzed for markers characteristics of stem cells (CD133); glial progenitors (PDGFRα, A2B5, O4, and CD44); and late oligodendrocyte progenitors (O1)." (PMID 18398462, 2008). "We have analyzed the expression of PDGFRα, A2B5, O4 and CD44 as surface markers for glial precursor cells, and CD133 for stem cells on freshly prepared glioma cells using flow cytometry." (PMID 18398462, 2008). "As in low-grade glioma cells, high-grade glioma cells analyzed in this study maintained the expression profiles for PDGFRα, A2B5, O4 and CD44." (PMID 18398462, 2008). "Irrespective of the grade and morphological diagnosis of gliomas, glioma cells concomitantly expressed PDGFRα, A2B5, O4, CD44 and GFAP." (PMID 18398462, 2008). "The protein-protein interaction (PPI) network analysis showed that ANXA5, STAT1, CD44, CAV1, ANXA2, and MAPT may serve as candidate biomarkers in glioma diagnosis." (PMID 40607003, 2025). "Notably, CD44 (2.45-fold, P < 0.001), CD133 (3.03-fold, P < 0.001), and Nanog (2.32-fold, P < 0.001) levels were markedly reduced in treated glioma cells with an IC50-value of CER compared to the control." (PMID 40133683, 2025). "Furthermore, the CHR + TMZ combination also significantly reduced the expression of stem cell markers CD133 and Nanog, and countered TMZ-induced increases in CD44, suggesting CHR mitigates glioma progression by reducing stem-cell characteristics." (PMID 40963691, 2025). "Microglial CD44 expression is elevated following stroke, ALS, glioma, and Alzheimer’s disease." (PMID 41282250, 2025). "Finally, six genes (ANXA5, STAT1, CD44, CAV1, MAPT, and ANXA2) with the highest degree values were selected as the hub genes for glioma by using the cytoHubba plugin for expression level and prognosis analyses." (PMID 40607003, 2025). "Hence, the mechanism of how ANXA5, STAT1, CD44, CAV1, MAPT, and ANXA2 contributed to the gliomas still need further research." (PMID 40607003, 2025). "In GSLCs and glioma tissues, Sohlh1 expression was negatively correlated with the expression of GSLC markers, such as Nestin, CD133, CD44, SOX2 and OCT4, whereas Sohlh1 expression was positively correlated with the expression of GSLC differentiation markers, such as MAP2, GFAP and MBP." (PMID 40418209, 2025). "In summary, a systematic bioinformatics analysis of DEGs demonstrated that ANXA5, STAT1, CD44, CAV1, MAPT, and ANXA2 might serve as potential biomarkers and therapeutic targets for glioma." (PMID 40607003, 2025).